CRP (C-reactive protein)
Diseases named in the same sentence as CRP in open-access papers (continued):
Sharing a sentence is not in itself a finding about the gene and the disease.
pneumonia (continued). "In a prospective cohort of critically ill patients with active neoplasia hospitalized for pneumonia, Rabello and colleagues observed that among surviving patients, there was a higher frequency of a rapid response to CRP (decrease > 60% on the fourth day of therapy) when compared to non-survivors." (PMID 39272020, 2024). "Therefore, the CRP level and other variables were suggested to be used as early warning signs of the onset of severe pneumonia." (PMID 39727640, 2024). "The excessive use of CRP when diagnosing pneumonia in primary care has been shown before." (PMID 38459974, 2024). "The levels of WBC and CRP were higher, while that of eGFR were lower in pneumonia group(P < 0.05)." (PMID 39736651, 2024). "Chest X-rays and CRP levels can be helpful in hospitalized children for whom physicians have difficulty deciding about antibiotic prescriptions, but their role in routinely classifying the severity of pneumonia in children is limited." (PMID 38449934, 2024). "Moreover, CXR and CRP are less often used in the assessment of patients with suspected pneumonia, while first-line antibiotics are more often used in primary care." (PMID 38459974, 2024). "CRP testing was performed in almost all of the patients of the cohort (99.5%), likely due to the need to differentiate between pulmonary embolism (PE) and other conditions like pneumonia, which can present with similar symptoms." (PMID 39458053, 2024). "The reduction in the pneumonia severity index between enrollment and discharge was more significant in the intervention group (p = 0.007); a significant decrease was also observed among patients who had C-reactive protein > 30 mg/L (p < 0.001)." (PMID 38383361, 2024). "After adding other MR models and sensitivity analyses, genus Roseburia was simultaneously associated adversely with CRP (Beta IVW = −0.040) and SAA1 (Beta IVW = −0.280), and family Bifidobacteriaceae was negatively associated with both CRP (Beta IVW = −0.034) and pneumonia risk (Beta IVW = −0.391)." (PMID 38585702, 2024). "Furthermore, post-transplant vitamin D levels and C-reactive protein (CRP) significantly impacted pneumonia incidence and survival outcomes." (PMID 39524045, 2024). "However, in case 1, after 2 weeks of combining ciprofloxacin and meropenem, the patient remained febrile and otherwise symptomatic (signs of pneumonia, swollen and inflamed joints, CRP increased) and treatment was continued." (PMID 38773469, 2024). "ROC-Curve aspect of the different sub-populations confirmed that these CRP levels can be used in patients with pneumonia (AUC 86.8%; 95% CI, 84.1–89.5) and severe patients (AUC 86.4%; 95% CI, 81.1–91.7) but we must remain cautious in immunosuppressed patients (AUC 82.1%; 95% CI, 70.2–94.0)." (PMID 38530466, 2024). "Post-transplant vitamin D levels and CRP significantly influenced pneumonia incidence and survival." (PMID 39524045, 2024). "In this study, we did not analyze the association between CRP and severe pneumonia due to the low critical illness rate and mortality of Omicron." (PMID 38215120, 2024). "Several studies have reported that biomarkers of inflammation (such as leukocyte count and its subtypes, NLR, C-reactive protein, procalcitonin, and interleukin-6) predicted SAP events in IS patients, and there was a strong association between NLR and pneumonia severity." (PMID 37537542, 2023). "Lung ultrasound examination, targeted to detect specific ultrasound patterns according to international recommendations, excluded pulmonary edema, pneumonia and pleural effusion, while blood tests showed a significant increase of the C-reactive protein (CRP) and neutrophilic leukocytosis." (PMID 37109368, 2023). "Therefore, it is important to monitor CRP levels to predict the occurrence of pneumonia and provide prompt treatment." (PMID 38063586, 2023).
pneumonia (continued). "Although the utility of CRP in the diagnosis of acute pneumonia and as a predictor of more severe disease with poor outcomes has been reported, the association of baseline CRP with future pneumonia risk has not been described." (PMID 38105941, 2023). "White blood cell count, C-reactive protein, procalcitonin, and myxovirus resistance protein A (MxA) levels were determined from blood samples in children (n = 24) hospitalized with radiologically verified pneumonia." (PMID 37009280, 2023). "Furthermore, the overall postoperative complication rate (pneumonia and UTIs) was increased in the patients with elevated serum-CRP levels and delayed surgery." (PMID 37107100, 2023). "Collectively, these events may lead to a further increase in body temperature and the levels of CRP and PCT, thus increasing the risk of pneumonia." (PMID 37731859, 2023). "Furthermore, patients with severe COVID-19 infection, often with critical pneumonia and systemic symptoms, showed high CRP levels, probably due to inflammatory factor storm." (PMID 38077346, 2023). "In our study, both the patients who developed pneumonia and those who required hospital treatment with oxygen therapy had significantly lower values of platelet and eosinophil counts and higher values of CRP, which is in line with previous studies by other authors." (PMID 37570378, 2023). "LDH and CRP are important in predicting not only the presence but also the severity of pneumonia." (PMID 37720137, 2023). "Based on the scientific evidence, CRP is not able to diagnose viral or bacterial cause of pneumonia nor to identify cases of mixed viral with bacterial co-infection." (PMID 36671362, 2023). "In addition, the delta-confirmed patients were significantly more likely than patients from the pre-delta period to have pneumonia (P < 0.001) or an elevated CRP level (P < 0.001)." (PMID 37256107, 2023). "The potential of CRP to identify the etiology of pneumonia has been extensively investigated." (PMID 36671362, 2023). "C-reactive protein (CRP) has been widely used in the management of pneumonia." (PMID 37238914, 2023). "They included intraabdominal abscess, pneumonia, urinary tract infection, profuse drain fluid with hypoalbuminemia requiring diuretics use, and unknown C-reactive protein elevation and were managed conservatively." (PMID 36895483, 2023). "Furthermore, the addition of routinely-available CRP to a model including clinical variables improved model performance for discrimination of pneumonia events." (PMID 38105941, 2023). "In the outpatient conditions, CRP levels can supply meaningful information to exclude pneumonia." (PMID 37296721, 2023). "This cis-acting model provided more evidence that CRP signalling through the protein itself is odds increasing for pneumonia, even though more complex relationships likely exist with factors like IL-6 signalling: OR per SD CRP = 1.16 [95% CI: 1.09, 1.23], P = 7.23 × 10−5." (PMID 35768473, 2022). "The highest number of patients with pneumonia was found in the CRP range of 20 to 50 mg/L." (PMID 36333682, 2022). "Studies have shown that CRP can improve the early diagnosis rate of pneumonia." (PMID 35991149, 2022). "Therefore, in the present study, we evaluated the value of S1P and CRP for discriminating COPD with pneumonia and AECOPD in an ED setting." (PMID 35307030, 2022). "Indeed, various biomarkers, including C-Reactive Protein, procalcitonin, lipocalin-2 and tumor necrosis factor-related apoptosis-inducing ligand have been evaluated for their ability to differentiate these pneumonia etiologies." (PMID 35115016, 2022). "The severity of pneumonia in this case was less extensive compared to the other two cases, and the CRP in dialysis patients with this disease may have indicated that their immune status may be relatively well maintained." (PMID 35182277, 2022). "In the present study, the increased CRP level was detected in children with severe pneumonia." (PMID 35665444, 2022).
pneumonia (continued). "In this study, compared with the mild symptom and pneumonia groups during the Omicron phase, older age, higher BMI, more non-vaccination, higher LDH, and higher CRP levels were associated with the pneumonia group." (PMID 35935257, 2022). "The multivariate analysis showed that older age, higher BMI, more non-vaccination, higher LDH, and higher CRP levels were associated with the pneumonia group." (PMID 35935257, 2022). "Although no obvious differences were observed between the unmatched and matched patient groups regarding perioperative markers of inflammation, pneumonia vice versa results in positive correlations with postoperative CRP values and leukocyte counts beyond postoperative days 3 or 4, respectively." (PMID 36104793, 2022). "The calculated PNEUMOINDEX consists of data obtained at admission, namely NYHA III & IV heart failure, COPD, generalized atherosclerosis, NIHHS score on admission, and CRP/Hgb ratio, and shows high accuracy in predicting hospital-acquired pneumonia in ischemic stroke patients." (PMID 36430028, 2022). "Other studies looked at the relation between CRP and pneumonia." (PMID 36333682, 2022). "A recent study performed in an acute Geriatrics Unit demonstrated that adding clinical and biochemical variables (including C-reactive protein) to LUS improved diagnostic accuracy, leading to a more accurate diagnosis of pneumonia in old patients with acute respiratory failure." (PMID 36553089, 2022). "The increased levels of ESR and CRP indicated inflammatory activity in the body, while an increased level of procalcitonin designated bacterial coinfection because the procalcitonin level increased in pneumonia and other diseases as well." (PMID 35997388, 2022). "Therefore, to better determine the type of pneumonia, clinical laboratory findings (such as routine blood tests, C-reactive protein, and blood culture) are needed." (PMID 36389379, 2022). "C-reactive protein (CRP) has been widely used in pneumonia management." (PMID 35307030, 2022). "Recent studies carried out on data of patients with arthritis or pneumonia suggest that NLR could provide better insight into subclinical inflammation compared to commonly used tests (C-reactive protein, white blood cell count)." (PMID 36101382, 2022). "Compared with the mild symptom and pneumonia groups in the Omicron group, older age, higher body mass index (BMI), higher non-vaccination, higher LDH, and higher CRP levels were associated with the pneumonia group." (PMID 35935257, 2022). "In correlation analyses, we found a rather strong and significant correlation between development of postoperative pneumonia, an infectious complication, which is regularly diagnosed during the early postoperative phase, and postoperative CRP values in statin( −) patients." (PMID 36104793, 2022). "From that dataset, 8 laboratory tests (lymphocyte count, platelets, CRP, D-dimer, creatinine, cardiac troponin I, aspartate aminotransferase, direct bilirubin) as well as two clinical parameters (age and severity of pneumonia) were derived and the nomogram was developed." (PMID 36304183, 2022). "The calculated PNEUMOINDEX consists of data obtained at admission, namely NYHA III and IV heart failure, COPD, generalized atherosclerosis, NIHHS score on admission, and CRP/Hgb ratio, and shows high prediction accuracy in predicting hospital-acquired pneumonia in ischemic stroke patients." (PMID 36430028, 2022). "This sudden change in Serum albumin level with rising C-reactive protein in four days immediately after admission in hospital ICU is hallmark of COVID-19 pneumonia which is not seen in other Pneumonias." (PMID 35480533, 2022). "Compared with the mild symptom and pneumonia groups during the Omicron phase, older age, higher BMI, more non-vaccination, higher LDH, and higher CRP levels were associated with the pneumonia group." (PMID 35935257, 2022).
pneumonia (continued). "Having pharyngeal erythema, fever, and pneumonia on chest X-ray, not having rhinorrhea, being girl, and having a higher CRP on admission were associated with a higher number of antimicrobial medications received during hospital treatment." (PMID 36497665, 2022). "Besides positive microbiological samples, pneumonia frequently presents with elevated markers of infection including C-reactive protein (CRP), an elevated or lowered white blood cell (WBC) count, and procalcitonin (PCT)." (PMID 33572924, 2021). "We observed that serum ferritin followed by D-dimer had better predictive accuracy in identifying patients with pneumonia compared with asymptomatic; and CRP in addition to the earlier markers had better accuracy for predicting severe illness compared with mild–moderate." (PMID 33988463, 2021). "In current research, the inflammatory response stimulated by pathogens such as viruses and bacteria is considered to be the pathogenesis of pneumonia in children, leading to high expression of serum levels of proinflammatory factors such as IL-6, IL-8, and CRP in children." (PMID 34956578, 2021). "However, it is plausible clinicians’ select antimicrobial treatment based on multiple factors such as CRP, indication for pneumonia, age and not only on a test result." (PMID 33903713, 2021). "However, in combination with an elevated CRP, it has been shown to be sensitive and specific for primary endpoint pneumonia." (PMID 34817224, 2021). "At multivariate logistic regression analyses, the only significant prognostic factors were duration of symptoms before hospitalization among the anamnestic factors, presence of fever and severe pneumonia among the clinical factors, and CRP levels among the biochemical factors." (PMID 33745060, 2021). "In addition, excessively increased inflammatory indicators (CRP, PCT) were observed in severe pneumonia cases caused by human adenovirus." (PMID 33593415, 2021). "CRP as a general systemic inflammation biomarker may help clinicians to make difficult therapeutic decisions for neonatal pneumonia." (PMID 34011087, 2021). "In our observation, also, we found that CRP, beyond its association with hsTnT, was related to the risk of ICU admission and requirement of mechanical ventilation, both outcomes defining the severity of the pneumonia." (PMID 33753759, 2021). "As pneumonia progresses, C-reactive protein levels are relatively higher in the most severe cases." (PMID 34211948, 2021). "Moreover, an increase in tomographic effectiveness has been reported (83.8% vs. 64.1%), and the CRP index improves with a consequent ameliorating of the clinical healing of subjects affected by pneumonia (78.9% vs. 66.2%)." (PMID 34072708, 2021). "The results showed that, although the CRP-involved multivariate model attained a relatively high validated AUC value of 0.81 (95% CI: 0.79–0.84) in distinguishing the overall pneumonia from URTI, it was still lower than our multivariate screening model recruiting LMR and NLR." (PMID 34861849, 2021). "Several clinical parameters were associated with the onset of CVF in ICUAP patients; nevertheless, in the multivariate analysis, SOFA score at the time of pneumonia diagnosis, need for orotracheal intubation and C-reactive protein three days after ICUAP diagnosis were the only predictors of CVF." (PMID 34209181, 2021). "Interestingly, A-T patients with IgA deficiency had a significant higher number of episodes with a significant elevation of CRP > 2 mg/dL and suffered more often from cutaneous granulomas and recurrent pneumonia." (PMID 34477998, 2021). "A multisite, international case-control study (Pneumonia Etiology Research for Child Health (PERCH)) in nine sites in seven countries reported a sensitivity of 77% and specificity of 82%, for a CRP cut-off of <37.1 mg/L, in differentiating RSV-associated pneumonia." (PMID 34306103, 2021). "But only one study investigated the CRP/MPV ratio in children with pneumonia." (PMID 34676267, 2021).
pneumonia (continued). "There is only one study in the literature evaluating the CRP/MPV ratio in children with pneumonia suggesting that the CRP/MPV ratio might be used in differentiating bacterial from viral pneumonia and prediction of complications." (PMID 34676267, 2021). "Saliva has been studied as an alternative biological fluid suitable for a noninvasive diagnostic and follow-up tool in neonatal infections including salivary CRP in the diagnosis of neonatal sepsis and pneumonia and screening of neonatal cytomegalovirus by salivary real-time PCR." (PMID 34708133, 2021). "When narrow-spectrum respiratory antibiotics (phenoxymethylpenicillin and amoxicillin) were prescribed for patients with pneumonia, the median CRP value was higher (72 mg/L) compared to when broad-spectrum respiratory antibiotics (doxycycline and erythromycin) were prescribed (50 mg/L) (P<0.001)." (PMID 32127365, 2020). "The likelihood of being diagnosed with pneumonia increased with increasing CRP level." (PMID 31650886, 2020). "When compared to controls, patients with PSD were significantly older, more often females, less often had left hemispheres stroke and treatment with recombinant tissue plasminogen activator (rt-PA), suffered from pneumonia, and had higher C-reactive protein (CRP) levels during hospitalization." (PMID 33213019, 2020). "In our study as in most previous reports, CRP outperformed PCT for the diagnosis of pneumonia." (PMID 32997689, 2020). "Serum C-reactive protein level elevation correlated with the bacterial species (p = 0.03), by which was increased in 80.0% of Haemophilus influenzae rhinosinusitis and 57.1% of Streptococcus pneumoniae rhinosinusitis." (PMID 30685351, 2020). "However, some demographic characteristics, symptoms, and laboratory parameters such as age, cough, sore throat, and CRP level can be used as a reference by clinicians to diagnose pneumonia." (PMID 33187475, 2020). "Looking at the interquartiles of the CRP level for pneumonia and acute bronchitis is interesting." (PMID 32127365, 2020). "In previous studies, the use of CRP tests has been shown to improve the diagnosis of pneumonia." (PMID 31650886, 2020). "A higher proportion of the severe pneumonia patient population had increased CRP and hs-CRP levels." (PMID 33065551, 2020). "Propensity of any degree of suspicion of pneumonia after CRP testing." (PMID 33399009, 2020). "In Sweden, CRP is recommended when the diagnosis of pneumonia is unclear." (PMID 33399009, 2020). "However, in home-based care settings, cases with CRP levels over 4.35 mg/dL and those with suspected pneumonia (and exceeding this level) need prompt medical attention." (PMID 32894233, 2020). "The National Institute for Health and Care Excellence (NICE) incorporated C-reactive protein (CRP) point-of-care tests (POCT) into the diagnosis of pneumonia guidelines CG 191 and CRP POCT is also included in the NICE acute cough summary for antimicrobial prescribing." (PMID 33153517, 2020). "For example, lymphocytes, neutrophils, CRP and others may be affected by complications such as chronic bronchitis, pneumonia." (PMID 33008382, 2020). "Interestingly, there were patients with pneumonia and urosepsis of bacterial origin presenting with S3 or S2 having normal CRP and a short febrile period (<2 days)." (PMID 32134948, 2020). "GPs who do not use CRP POCT reported more frequently than those who do use CRP POCT starting symptom management in case pneumonia is confirmed (neutral to almost always 15% vs 9%; p = 0.05) or ruled out with chest X-ray (neutral to almost always 57% vs 41%; p <0.01)." (PMID 31455104, 2019). "Based on these AUCs, we further assessed the sensitivity, specificity, PPV and NPV at CRP cut-offs of ≥ 40 mg/L, ≥ 60 mg/L and ≥ 100 mg/L, for differentiating bacterial from presumed viral plus other pneumonias, and definite bacterial from presumed viral pneumonias." (PMID 30940126, 2019).